MIR518E (microRNA 518e)
Synonyms: hsa-mir-518e; MIRN518E; mir-518e
Gene: MicroRNA gene on chromosome 19 (53,729,838 to 53,729,925, forward strand). Ensembl gene ENSG00000207987.
Gene Ontology:
Biological process: miRNA-mediated post-transcriptional gene silencing
Homologues: Orthologues: chimpanzee ptr-mir-518e (100% identical), macaque mml-mir-523b (92% identical), macaque mml-mir-518g (60% identical). Paralogues in human: MIR522 (91% identical), MIR523 (90% identical), MIR516A1 (89% identical), MIR518F (89% identical), MIR516A2 (88% identical), MIR518C (88% identical), MIR516B1 (86% identical), MIR518D (86% identical), MIR519A2 (86% identical), MIR521-1 (86% identical), MIR519C (85% identical), MIR520C (85% identical), and 12 more.